ETV6 (ETS variant transcription factor 6)
Diseases named in the same sentence as ETV6 in open-access papers (continued):
Sharing a sentence is not in itself a finding about the gene and the disease.
acinic cell carcinoma (7 papers, 2017 to 2025). "By contrast, deletion of one copy of the ETV6 gene has been observed in isolated cases of acinic cell carcinoma." (PMID 39101978, 2024). "Prior to IHC and ETV6 gene detection in the current study, four of the 23 patients’ tumors were misdiagnosed as acinar cell carcinomas, three as mucoepidermoid carcinomas, two as adenoid cystic carcinomas, one as low-grade ductal carcinoma, and one as squamous cell carcinoma." (PMID 34811395, 2021). "The 3 ETV6 translocation-negative secretory carcinomas originally diagnosed as zymogen granule-poor acinic cell carcinoma posed a diagnostic dilemma." (PMID 31822803, 2020). "However, carcinomas may frequently display a diffuse oncocytic phenotype, being classified by their characteristic features (e.g., AR-positive salivary duct carcinoma, MEC with MAML2 rearrangements, secretory carcinoma with ETV6 NTRK3 gene fusion, and DOG1- and SOX10-positive acinic cell carcinoma)." (PMID 41440486, 2025).
B-cell precursor acute lymphoblastic leukemia (7 papers, 2016 to 2025). "Autophagy inhibition, spleen tyrosine kinase (SYK), and IGF2BP1 are potential future therapeutic targets for ETV6::RUNX1-driven B-cell precursor acute lymphoblastic leukemia due to their roles in ETV6::RUNX1 cell survival and prognosis." (PMID 38811988, 2024).
Myelodysplasia (7 papers, 2013 to 2025). Clonal hematopoietic stem cell disorders characterized by dysplasia (ineffective production) in one or more hematopoietic cell lineages, leading to anemia and cytopenia. "The co-occurrence of two different myelodysplasia-associated somatic variants (CUX1/ETV6 and ASXL1/BCOR) was observed in 2 patients." (PMID 41188636, 2025). "Overall, our results indicate that genetic disruption of ETV6 results in deregulation of interferon response genes, perhaps generating a proinflammatory bone marrow environment that affects megakaryopoiesis and overall hematopoiesis, predisposing to the development of myelodysplasia." (PMID 32841218, 2020). "Eight myelodysplasia-associated somatic variants in the BCOR/BCORL1, DNMT3A, ASXL1, CUX1, and ETV6 genes were found in 7 patients (5 AA and 2 MDS-h patients, 17%); neither AA patient had evidence of myelodysplasia at the time of analysis." (PMID 41188636, 2025).
acute leukemia (6 papers, 2011 to 2025). A clonal (malignant) hematopoietic disorder with an acute onset, affecting the bone marrow and the peripheral blood. "However, ETV6 has been highly discussed in relation to adult acute leukemia, which is associated with juvenile cells, while DLBCL is mainly linked to mature cells." (PMID 29992138, 2018).
chronic eosinophilic leukemia (6 papers, 2013 to 2026). "We report the first documented case of chronic eosinophilic leukemia (CEL) with ETV6-SYK gene rearrangement manifesting as refractory bilateral nodular scleritis within a broader paraneoplastic autoimmune syndrome." (PMID 42005114, 2026). "Other examples of deregulated tyrosine kinases fusion genes which are found in myeloid malignancies include TEL-ABL, TEL-JAK2, FLT3/ITD in acute myeloid leukemia (AML), ETV6-PDGFRB (TEL-PDGFRB) in chronic myelomonocytic leukemia (CMML), and FIP1L-PDGFRA in chronic eosinophilic leukemia (CEL)." (PMID 24116232, 2013).
congenital fibrosarcoma (6 papers, 2019 to 2025). A fibrosarcoma that occurs in infants. "In addition, a repeated gene fusion of ETV6 and NTRK3 (ETV6‐NTRK3) has been defined in congenital fibrosarcoma." (PMID 32724874, 2020).
Down syndrome (6 papers, 2015 to 2026). "Notably, Down syndrome is highly prevalent and associated with a worse outcome in ETV6::RUNX1-like ALL." (PMID 42007448, 2026). "Many genetic factors have been shown to be associated with an increased risk of ALL, including Down syndrome, germline mutations in PAX5 and ETV6 and polymorphic variants in specific genes." (PMID 40122536, 2025). "Significant factors such as ETV6 RUNX1 fusion status, karyotype, MRD day 29, Down syndrome, and DNA index were applied to construct a prognostic nomogram." (PMID 33014835, 2020).
lymphoma (6 papers, 2018 to 2025). A malignant (clonal) proliferation of B- lymphocytes or T- lymphocytes which involves the lymph nodes, bone marrow and/or extranodal sites. "A mutational analysis of primary central nervous system lymphoma also revealed that ETV6 might be an underlying target for this kind of lymphoma treatment." (PMID 29992138, 2018). "We found that lymphoma patients with high ETV6/PIM2 ratios (>1) had a worse outcome compared to patients with low ETV6/PIM2 ratios (<1; p = 0.01)." (PMID 35053500, 2022). "Examination of the link between FOXO1:ETV6 and lymphomas reveals that their joint expression levels improve patient clinical outcome stratification." (PMID 31913281, 2020). "An analysis of a representative dataset (Salaverria lymphoma) revealed that MME expression levels were significantly higher in the GCB subtype than those in the ABC subtype and that IL2RA, ETV6, and CCND2 expression levels were higher in the ABC subtype than those in the GCB subtype." (PMID 29992138, 2018).
prostate carcinoma (6 papers, 2009 to 2022). A carcinoma that arises from epithelial cells of the prostate gland. "In summary, we concluded that TWIST1 is negatively associated with ETV6 and is involved in tumor progression in human prostate cancer." (PMID 29455655, 2018). "We demonstrated that ETV6 efficiently suppressed metastasis of prostate cancer; however, the underlying mechanism remained unclear." (PMID 29455655, 2018). "Since resistance to EGFR antagonists eventually develops and remains a challenging phenomenon, it is possible that loss of ETV6 function promotes the development of drug resistance in prostate cancer." (PMID 29455655, 2018). "Mutational inactivation of ETV6 was found in prostate cancer." (PMID 36292767, 2022). "In PCa, mutational analysis of ETV6 in prostate carcinoma cell lines, xenografts, and metastatic foci revealed that an inactive protein might be produced that acts as a tumor-suppressor gene." (PMID 31181727, 2019). "ETS variant gene 6 (ETV6) is a putative tumor suppressor and repressed by epidermal growth factor receptor (EGFR) signaling in prostate cancer." (PMID 29455655, 2018). "Our results support a novel EGFR-ETV6-TWIST1 pathway in that ETV6 serves as a gatekeeper to maintain TWIST1 at low levels in prostate cancer." (PMID 29455655, 2018). "Prostate cancer cells with ETV6-knockdown are insensitive to TKIs while exogenous expression of ETV6 restores the anti-proliferative effects in the TKI-resistant RasB1 cell line, which expresses a mutated RAS oncogene." (PMID 29455655, 2018). "Prostate cancer still at earlier or hormone-sensitive stages containing intact ETV6 activity could be responsive to EGFR-targeted antagonists as monotherapy." (PMID 29455655, 2018). "Our studies provide a novel and testable hypothesis that connects ETV6-TWIST1 signaling to EGFR-TKI resistance during prostate cancer progression." (PMID 29455655, 2018). "In human prostate cancer cells, ETV6 also inhibits TWIST1 expression and ETV6-knockdown can promote TWIST1-dependent malignant phenotypes." (PMID 29455655, 2018). "We further investigated the relationship between ETV6 and TWIST1 in human prostate cancer tissues collected from the Taipei Medical University Joint human biological database (approval no.: 201,311,034, Taipei, Taiwan)." (PMID 29455655, 2018). "In non-metastatic prostate cancer cells, which express more ETV6 compared to RasB1, ETV6 knockdown efficiently increased TWIST1 at both the mRNA and protein levels, suggesting that TWIST1 is tightly controlled by ETV6." (PMID 29455655, 2018). "Since EGFR-based therapeutics showed no beneficial effects in prostate cancer, it is important to determine whether the ETV6-TWIST1 axis plays a role in the development of drug resistance." (PMID 29455655, 2018). "To further confirm the negative relationship between ETV6 and TWIST1 in human prostate cancer, we analyzed two public prostate cancer datasets." (PMID 29455655, 2018).
childhood leukemia (5 papers, 2008 to 2023). An acute or chronic leukemia that occurs during childhood. "High hyperdiploid B-cell ALL and ETV6/RUNX1-positive pediatric ALL are among the most common subtypes of childhood leukemia." (PMID 37685286, 2023). "Genetic alterations affecting the process of megakaryopoiesis, such as MYH-9, ETV6, RUNX1, and ANKRD26 variants, have been reported to cause leukemic progression and are especially related to the genetic predisposition of childhood leukemia." (PMID 36534659, 2022). "In this study, we characterized the lncRNA expression signature associated with ETV6/RUNX1-positive BCP-ALL, one of the most prevalent genetic subtypes of childhood leukemia." (PMID 27650541, 2016). "Accumulating genetic and functional evidence point to ETV6 as being the tumour suppressor gene targeted by the deletions at chromosome 12p12-13 found in various cancers, particularly childhood leukemia." (PMID 19259410, 2008).
mesenchymal neoplasms (5 papers, 2020 to 2025). "To date, most of the fusions described in mesenchymal neoplasms involve NTRK1 and NTRK3 genes and include different fusion partner genes, most common being ETV6, LMNA, and TPM3." (PMID 32860002, 2021). "Thus, while ETV6::NTRK3 fusion identifies the homogeneous group of IF and the renal counterpart (cellular or mixed CMN), EGFR‐KDD mesenchymal neoplasms are a heterogeneous group of mesenchymal neoplasms which deserve further investigation." (PMID 40178433, 2025).
non-small cell lung carcinoma (5 papers, 2019 to 2022). A group of at least three distinct histological types of lung cancer, including non-small cell squamous cell carcinoma, adenocarcinoma, and large cell carcinoma. "The overexpression of ETV6 has also been reported in non-small-cell lung cancer and nasopharyngeal carcinoma, suggesting an oncogenic role of ETV6." (PMID 36292767, 2022). "Overexpression of ETV6 correlated with poor prognosis for non-small-cell lung cancer and for nasopharyngeal carcinoma." (PMID 36292767, 2022).
adenoid cystic carcinoma (4 papers, 2019 to 2025). A malignant tumor arising from the epithelial cells. "FISH was particularly helpful for diagnosing malignant tumours (mucoepidermoid carcinoma with a MECT1-MAML2 fusion, adenoid cystic carcinoma with a MYB translocation and secretory carcinoma with an ETV6 translocation)." (PMID 31805712, 2019).
mucoepidermoid carcinoma (4 papers, 2019 to 2026). A carcinoma morphologically characterized the presence of cuboidal mucous cells, goblet-like mucous cells, squamoid cells, cystic changes, and a fibrotic stromal formation. "These include fusions of the ETV6 gene in secretory carcinoma (SC), MYB/MYBL1::NFIB in adenoid cystic carcinoma (AdCC), CRTC1/CRTC3::MAML2 in mucoepidermoid carcinoma (MEC), and EWSR1::ATF1 in hyalinizing clear cell carcinoma as the most frequent and best characterized gene fusions." (PMID 38217715, 2024).
nasopharyngeal carcinoma (4 papers, 2020 to 2023). A carcinoma arising from the nasopharyngeal epithelium. "Treatment with the BRD4 inhibitor JQ1 significantly suppresses super-enhancer-associated ETV6 gene expression and induces nasopharyngeal carcinoma cell growth inhibition." (PMID 38135679, 2023). "In nasopharyngeal carcinoma cells, super-enhancers are enriched of BRD4, NF-κB, IRF1 and IRF2 transcription factors at the loci of critical oncogenes such as ETV6, high expression of which in human nasopharyngeal carcinoma tissues is correlated with poor patient prognosis." (PMID 38135679, 2023). "Interestingly, EBV infection also induces nasopharyngeal carcinoma (NPC)-specific SE generation in ETV6 introns and coding regions, which increases ETV6 expression correlated with poor prognosis." (PMID 32278350, 2020).
sarcoma (4 papers, 2022 to 2025). A usually aggressive malignant neoplasm of the soft tissue or bone. "This EPO-GEMM (EPO-based genetically engineered mouse model) platform allows the generation of ten genetically distinct sarcomas on an isogenic background, including the first model of ETV6::NTRK3-driven sarcoma." (PMID 40523919, 2025). "We demonstrate the feasibility of preclinical testing in mouse sarcoma cell lines and immunocompetent sarcoma SAMs using NTRK inhibitor treatment in ETV6::NTRK3-driven sarcomas." (PMID 40523919, 2025). "Finally, HLA and APP transcript levels were heterogeneous in NRSTS, with only one undifferentiated sarcoma with a ETV6::NTRK3 fusion displaying high transcript levels and IHC score, and were negligible in a single EP PDX." (PMID 38318504, 2023). "On the other hand, sarcomas with fusions of the NTRK3 gene and especially those with ETV6 fusion partner, are mainly aggressive neoplasms, even those with intermediate cytological atypia." (PMID 35645621, 2022).
breast tumors (3 papers, 2009 to 2019). "To validate PSIONIC-derived prognostic TFs, we perform immunohistochemical analyses in 31 uterine serous tumors for ETV6 and 45 basal breast tumors for MITF and confirm that the corresponding protein expression patterns are also significantly associated with prognosis." (PMID 31554806, 2019). "The unique ETV6/NTRK3 fusion provides a further way to distinguish SBC from other breast tumors." (PMID 31443715, 2019).
central nervous system lymphoma (3 papers, 2018 to 2024). "Additionally, ETV6 is also closely linked to primary central nervous system lymphoma (PCNSL)." (PMID 36914737, 2023).
colon cancer (3 papers, 2016 to 2024). "The eQTL analysis from TCGA data also revealed that rs2238126 was an eQTL for the ETV6 and BCL2L14 genes in colon tumour." (PMID 27145994, 2016). "We found that rs2238126 was an eQTL for the ETV6 (PANOVA=3.46 × 10−3) and BCL2L14 (PANOVA=0.017) genes in colon tumour tissues but not in normal colon tissues (ETV6, PANOVA=0.169; BCL2L14, PANOVA=0.578)." (PMID 27145994, 2016).
COVID-19 (3 papers, 2021 to 2025). A disease caused by infection with severe acute respiratory syndrome coronavirus 2. "Consistently, the regulons including GATA2, SPI1, ETS2, FLI1, and ETV6 were activated in COVID-19 patients." (PMID 34349096, 2021). "Up-regulation of ETS2, FLI1, GATA2, and ETV6 in the HSC/MPPs of COVID-19 patients raised the speculation that the HSC/MPPs preferentially differentiated into MkP cells." (PMID 34349096, 2021). "By 6 weeks post-inclusion, COVID-19 hypermethylation of genes with the highest fold-change compared to healthy controls included FAM178B, FYN, TMCC1, TMEM212-AS1, and FIG4, while the top five hypomethylated genes were GIT2, PDGFRB, SEMA6D, TNFAIP8, and ETV6." (PMID 41227320, 2025).
glomerulonephritis (3 papers, 2013 to 2019). A renal disorder characterized by damage in the glomeruli. "BCL2 transgenic and ETV6/RUNX1;BCL2 double transgenic mice develop a glomerulonephritis phenotype over time, which was displayed by staining of kidney sections." (PMID 31404120, 2019). "Our study therefore demonstrates a novel cooperative activity of ETV6/RUNX1 and BCL2 for glomerulonephritis and lymphoma development." (PMID 26919255, 2016). "In addition, as the ETV6/RUNX1 fusion is frequently observed in newborn children, individual autoimmune or immune complex glomerulonephritis patients harboring the ETV6/RUNX1 fusion (in plasma B cells) could exist exhibiting an aggravated glomerulonephritis phenotype." (PMID 26919255, 2016).
lymphoid leukemia (3 papers, 2013 to 2022). A malignant lymphocytic neoplasm of B-cell or T-cell lineage involving primarily the bone marrow and the peripheral blood. "While ETV6 is frequently rearranged or fused with other genes in human myeloid and lymphoid leukemias, it is only rarely altered in B-cell lymphoma." (PMID 35053500, 2022). "Together with reports of FOXO1 and ETV6 as putative tumor suppressors in lymphomas this suggests an important role of this TF pair in lymphoid leukemia." (PMID 31913281, 2020). "We examined this concept using available data on lymphoid leukemia patients to examine the effect of predicted associations with cooperative binding of FOXO1 and ETV6 (DOID:0050745, k-mer GAAAACCGAANM; mean k-mers Z-score = 3.2)." (PMID 31913281, 2020).
mesoblastic nephroma (3 papers, 2014 to 2025). A solid, unencapsulated tumor of the kidney composed of spindle mesenchymal cells that resemble fibroblasts or muscle cells. "The authors also suggest a potential relationship with mixed and classic mesoblastic nephroma, both carrying EGFR‐KDDs, while it is found very rarely in cellular mesoblastic nephroma, which is considered the renal counterpart of IF, characterized by ETV6::NTRK3 fusion." (PMID 40178433, 2025).
myeloproliferative neoplasm (3 papers, 2020 to 2025). A clonal hematopoietic stem cell disorder, characterized by proliferation in the bone marrow of one or more of the myeloid (i.e., granulocytic, erythroid, megakaryocytic, and mast cell) lineages. "We report a case of extramedullary involvement and leukemic transformation in myeloproliferative neoplasm (MPN), where ETV6::ABL1 was initially overlooked but later detected in the blast phase." (PMID 39066837, 2024).
neuroblastoma (3 papers, 2022 to 2025). Neuroblastoma (NB) is the most common solid, extracranial childhood tumor. "These genes included neuroblastoma-amplified sequence (NBAS), ETS variant transcription factor 6 (ETV6), transmembrane protein 165 (TMEM165), collagen type IV alpha-3-binding protein (C43BP), serine/threonine-protein phosphatase 5 (PPP5), and short-chain specific acyl-CoA dehydrogenase (ACADS)." (PMID 39400548, 2025).
squamous cell carcinoma (3 papers, 2021 to 2025). A carcinoma arising from squamous epithelial cells. "These include, among others, the identification of a subset of sinonasal carcinomas associated with HPV infection, the identification of a subset of squamous cell carcinomas with EGFR alterations, and of rare variants with chromosomal translocations (DEK::AFF2, ETV6::NTRK and others)." (PMID 35326613, 2022). "Interestingly, SplitFusion detected novel fusions that have not been reported previously in lung cancer, including one squamous cell carcinoma with FGFR3::JAKMP1 fusion, one adenocarcinoma with CLIP2::BRAF fusions (two fusion isoforms in one tumor), and one adenocarcinoma with ITPR2::ETV6 fusion." (PMID 40041857, 2025).
angioedema (2 papers, 2020 to 2025). Swelling involving the deep dermis, subcutaneous, or submucosal tissues, representing localized edema. "In contrast, variations in ETV6 are linked to a greater risk of angioedema associated with ACEIs197." (PMID 40640196, 2025). "Variants in immune-regulating genes (ETV6) and protein kinase C (PRKCQ) are risk factors for the side effects of ACEI, including angioedema." (PMID 40640196, 2025). "ETV6, BDKRB2, MME, and PRKCQ were nominally associated with angioedema (p < 0.05), but none of the candidate genes was significantly associated after correction with multiple testing (p < 2.89 × 10−5)." (PMID 32080354, 2020). "In the candidate gene analysis, ETV6, BDKRB2, MME, and PRKCQ were nominally associated with angioedema (p < 0.05), but did not pass Bonferroni correction for multiple testing (p < 2.89 × 10−5)." (PMID 32080354, 2020). "The main findings were a non-significant association between risk of angioedema and the ETS Variant Transcription Factor 6 gene (ETV6) in African Americans, while a variant of the Protein Kinase C Theta gene (PRKCQ) tended to be protective in European Americans." (PMID 32080354, 2020).
astrocytoma (2 papers, 2022). "The expression of ETV6 was significantly higher in astrocytoma than oligodendroglioma." (PMID 36292767, 2022).